RNU6-362P (RNA, U6 small nuclear 362, pseudogene)
Gene: Small nuclear RNA gene on chromosome 17 (75,031,097 to 75,031,186, forward strand). Ensembl gene ENSG00000252545.
Homologues: Orthologues: macaque U6 (63% identical). Paralogues in human: RNU6-1316P (70% identical), RNU6-24P (70% identical), RNU6-338P (70% identical), RNU6-641P (70% identical), RNU6-1060P (69% identical), RNU6-1201P (69% identical), RNU6-207P (69% identical), RNU6-50P (69% identical), RNU6-517P (69% identical), RNU6-560P (69% identical), RNU6-623P (69% identical), RNU6-650P (69% identical), and 1283 more.